TNF (tumor necrosis factor)
Diseases named in the same sentence as TNF in open-access papers (continued):
Sharing a sentence is not in itself a finding about the gene and the disease.
infection (continued). "In this study we observed lower bacterial burden at the infection site of Ppara-/- mice compared to C57BL/6 mice, but the levels IL-6 and TNF-α elicited by S. aureus infection were equally robust in both mouse lines." (PMID 38601738, 2024). "Our data showed that infected cells produced TNF-α (48.5 ± 23 ng/mL in MDMs and 187 ± 18 ng/mL in THP-Ms) 24 h post-infection." (PMID 38672491, 2024). "The activation of TLR2 leads to the release of pro‐inflammatory cytokines such as IL‐6 and TNF‐α, which can help suppress CDI symptoms and prevent both the initial occurrence and recurrence of the infection." (PMID 38898983, 2024). "In the course of mycobacterial infections TNFα induces the expression of chemokines, such as IL-8, MCP-1 and RANTES that send signals for the migration of immune system cells to the sites of infection." (PMID 38399810, 2024). "Upon infection with SARS-CoV-2, the human immune system can become overactivated, releasing large amounts of cytokines, such as tumor necrosis factor-α (TNF-α) and IL-6, triggering an excessive inflammatory response." (PMID 39717543, 2024). "However, this variant infection induced a lower amount of Interleukin 1β (IL-1β) and macrophage inflammatory protein-1α (MIP-1α) compared to the wild-type, In the other hand, the Alpha variant triggered a considerable level of TNF-α (14.73 pg/mL) and a modest rise of IP-10 level than wild type." (PMID 38568894, 2024). "We measured the abundance of TNF-α and IL-6 in the thigh muscle tissue and found similar levels of both cytokines in C57BL/6 and Ppara-/- infections." (PMID 38601738, 2024). "Infection with HPV results in the activation of the host immune system and, among other, the release of a wide range of cytokine like TNFα." (PMID 38125616, 2024). "These macrophages, in turn, upregulate anti-inflammatory cytokines such as interleukin-10 (IL-10) and downregulate the proinflammatory cytokines such as IL-6 and tumor necrosis factor (TNF-α), which helps in the spread of the infection." (PMID 39204243, 2024). "On the other hand, infection of cardiomyocytes with either QRO or CI2 isolates and further stimulation with TNF-α + IFN-γ inhibited NOS2 expression and NO production, leading to amelioration of infection." (PMID 39452749, 2024). "During the acute infection stage, the serum levels of IFN-γ and TNF-α were increased, and the receptor genes for these cytokines were found upregulated in monocytes." (PMID 38898888, 2024). "At 48 h of infection, the gene expression of CXCL10, TNF-α, IL-8, and IL-6 was increased up to 47.14-fold, 26.43-fold, 10.87-fold, and 3.45-fold, respectively, while the COX-2 gene was expressed 70.70-fold after 72 h of dengue viral infection." (PMID 39200005, 2024). "Analyses of cytokines gene expression in the ileum showed that EGS infection promoted increased expression of NLRP3, IL-1β, and TNF in WT-infected when compared with WT-uninfected mice." (PMID 39267751, 2024). "We validated this in the context of TNF-α release from macrophages and indeed demonstrated increase in TNF-α in cell culture supernatants following infection, which was significantly reduced with AN_CH_37." (PMID 38590438, 2024). "The infection stage group had higher content of PCT, TNF‐α, and IL‐6 and lower content of Beclin‐1 and LC3 than the infection control group (p < .001)." (PMID 38577990, 2024). "In either MCMV or HCMV, vICA appears critical to infection of myeloid cells, and studies with MCMV M36 mutant viruses implicate control over TNF-dependent cell death in a variety of cell types." (PMID 39772130, 2024). "Astrocytes can activate innate antiviral pathways upon infection with HSV-1–such as IL-6, TNF-α, and type I IFN production via the TLR3-dependent pathway in HSV-2 infection." (PMID 39339840, 2024).
infection (continued). "In contrast, the transcription levels of IL-6 (P < 0.001, ***), IL-8 (P < 0.001, ***), and TNF-α (P < 0.001, ***) were significantly lower in PAM Cl3 cells infected with vL126A/ΔNLS compared to vWT infection." (PMID 38547254, 2024). "TNF-α, IFN-γ, IL-1β, IL-6, and MIF are pro-inflammatory molecules that activate immune cells and defend against infection." (PMID 38572322, 2024). "When administered after the onset of infection and again 24 h later, MFX effectively reduces cytokine levels—including IL-1β, TNF-α and IL-6—as well as organ lesion markers, such as LDH, ALT and urea." (PMID 39200042, 2024). "We observed significantly elevated TNF-α levels in lncCYPB, CYPB, and dCYPB knockdown cells, both under control conditions and during infection." (PMID 39711545, 2024). "Among the six cyto/chemokines detectable by the array, we observed a significant rise in MCP1, TNFα, and interleukin 6 (IL6) in JEV-infected N9 cells at 6 h post-infection (HPI) and 24 HPI." (PMID 38869276, 2024). "After infection with H. pylori, the gene expressions of abundant proinflammatory cytokines in AGS cells, including TNF-α, IL-6, COX-2, IL-8, and IL-16, were upregulated significantly (p < 0.05)." (PMID 38891033, 2024). "(I) Differential interaction strengths of a cellular interactome for TNF, SPP1, and CXCL signaling pathways between all cell types in infection." (PMID 38767331, 2024). "On the other hand, the increased levels of C3, IL-6, IL-12, TNFα and CXCL1 as a means of activation of innate-mediated response in early infection phases have been found in SARS-CoV-2-infected Caco-2 cells." (PMID 38886736, 2024). "We found that expression of NF-κB target genes TNF-α, IFN-γ, IL-6 and IL-8 were modulated during the course of infection." (PMID 39325775, 2024). "Pro-inflammatory cytokines like tumor necrosis factor (TNF), interleukin-1 (IL-1), and interleukin-6 (IL-6) are central to this process, driving the migration of cells to the infection sites." (PMID 39590344, 2024). "We observed significantly increased expression of TNF-α, IL8, MCP, and STAT1 genes in trained macrophages upon infection by both the Mtb strains, similar to those observed in trained and restimulated macrophages." (PMID 38980014, 2024). "We observed a decrease in IL-1β, IL-6, TNF, and IFNβ levels in the supernatants of GSDMD knockdown (KD) macrophages despite comparable levels of infection as indicated by viral nucleoprotein levels in Western blots." (PMID 38553499, 2024). "After infection with ASFV, the concentrations of porcine TNF-α and IL-1β were significantly elevated in supernatants of PAMs and BMDMs in a time-dependent manner." (PMID 38952452, 2024). "We found that TNF-α, IL-β, CXCL2, TLR4, and IL-6 (mRNA) and selected proteins (TNF-α, IL-1β, and CXCL2) were upregulated significantly by exposure to the particulate and infection." (PMID 38928968, 2024). "Next, we further analyzed the DEGs in dMφ subsets (TNF+dMφ, CD86+dMφ, CD163+dMφ, and TGFβ+dMφ) after infection." (PMID 38730500, 2024). "To determine the specific mechanism, we examined the levels of apoptosis-related genes (BAX, APAF-1, TNF-α, Caspase-9, Caspase-3, and BCL-2) in EBL cells following infection with M. bovis." (PMID 39308873, 2024). "As ITA is an immunomodulatory agent, we measured the pro-inflammatory cytokines TNF, IL-6, and IL-1β, and the anti-inflammatory cytokine IL-10 in cell culture supernatants 24 hours after NMII infection of Acod1+/- and Acod1-/- BMM." (PMID 39156902, 2024). "The infection stage group had much higher content of PCT, TNF‐α, and IL‐6 than the infection control group (p < .001)." (PMID 38577990, 2024). "Further, our data indicate that UL26 is necessary to broadly restrict STAT family member activation during infection and that UL26 is sufficient to attenuate cytokine-induced IFNα and TNFα signaling." (PMID 38768227, 2024).
infection (continued). "This adaptive immunity includes promoting Th1 responses to produce proinflammatory cytokines, such as IL-1β, IL-18, IL-12, tumor necrosis factor (TNF-α), and interferon (IFN)-γ to effectively clear the infection." (PMID 38623843, 2024). "The discussion emphasizes the need for a better understanding of the role of the TNF/TNFRI axis, especially in the post-infection context, as elevated sTNF-α levels in post-COVID individuals have been previously correlated with long COVID syndrome." (PMID 39335653, 2024). "On the fifth day after infection, a high dose of GUANKE reduced the induction of TNF-α, IL-1β, IL-6, and IL-17." (PMID 39431894, 2024). "Cytokines, such as interleukin (IL)-1, IL-6, and tumor necrosis factor (TNF)-α, work together to activate immune cells, regulate epithelial and fibroblast cells, and prevent infection." (PMID 39335453, 2024). "The gene expression levels of the pro-inflammatory cytokines, including IL-6, TNF-α, and CCL2, were significantly elevated in the infection group compared to the control group (P < 0.01 and P < 0.05, respectively; n = 5; Tukey test)." (PMID 38233485, 2024). "The effect of MEndoB on survival, S. aureus CFU counts, and levels of the cytokine tumor necrosis factor alpha (TNF-α), a marker for infection and inflammation, were determined for three different single doses over 48 h." (PMID 38275913, 2024). "We found that neonatal mouse cardiomyocytes stimulated with TNF-α + IFN-γ produced even more nitrite than BMMΦ (more than 70 μM), and this production noticeably diminished with the infection with both T. cruzi isolates." (PMID 39452749, 2024). "During primary and secondary infection, Salmonella is dependent on IL-12, IFN-γ, and tumor necrosis factor α (TNF-α)." (PMID 39771981, 2024). "NK cells mediate cytotoxicity against dysfunctional cells, for example after damage or infection, and produce pro-inflammatory cytokines, e.g. interferon-γ (IFN-γ) and tumor necrosis factor-α (TNF-α), and chemokines, such as CC chemokine ligand 5 (CCL5)." (PMID 39355242, 2024). "A weak positive expression of TNF-α was observed in the epithelial and vascular endothelial cells of the PAD-2 and NYS groups, with lighter staining than the infection and PAD-1 groups." (PMID 38708351, 2024). "Through intercellular communication analysis, inflammatory signaling pathways, such as the CCL, TNF, CXCL, complex, and ALCAM pathways, were found to increase and enhance cellular communication after infection." (PMID 39590301, 2024). "We used acute infection with M. pneumoniae, and this modality results in a Th1-type immune response, so we screened for the presence of the Th1 cytokines IFN-γ, TNFα, functional IL-8 (CXCL1) in BALF following infection." (PMID 39759447, 2024). "Our first observation indicated that the presence As during the 6 h infection of S. aureus infection of MAC-T cells led to a dose dependent and significant reduction in IL6, IL1β, IL8 and TNFα produced by the infected cells." (PMID 38414081, 2024). "Inflammatory cytokines, including interleukin 6 (IL-6), interleukin 1β (IL-1β), and tumor necrosis factor-alpha (TNF-α) are secreted by microglia within the brain in response to injury and infection." (PMID 39000602, 2024). "The mice that received cidal (cipro) treated cEC1 had statistically significantly higher serum levels of TNF, IL12p40, and CCL3 at 1 h post infection than the mice that received static (tet) treated cEC1." (PMID 39609397, 2024). "It was reported that TNF-α plays a key role in lung injury during HP-PRRSV-infection, and STAT1 can upregulated TNF-α expression." (PMID 38590524, 2024). "We previously showed that infection with RSV wt increased the expression of CCL5 and TNF-α proteins, and that this increase was less with mutants lacking either or both NS proteins." (PMID 38932114, 2024).
infection (continued). "Taken together, ITA and its isomers MES and CTC have an overall similar immunomodulatory effect on production of the cytokines IL6, TNFα, IL1β and IL10 in response to infection with C. burnetii." (PMID 39156902, 2024). "Forty-eight hours after G. parasuis challenge, IL-1β, IL-10, IL-18, TNF-α and IFN-γ mRNA expression was increased, and IL-2 and IL-8 mRNA expression was decreased in the infection group compared to the control group (P < 0.001)." (PMID 39075562, 2024). "This interleukin induces the production of TNF-a and IL-1β, as well as CXC chemokines involved in the recruitment and activation of Mφ and neutrophils in various models of infection." (PMID 38248954, 2024). "We previously have found that UL26 is sufficient to antagonize TNFα-mediated NFκB activation and is necessary to prevent the induction of interferon-stimulated gene (ISG) expression during infection." (PMID 38768227, 2024). "TNF-α, another chemokine whose expression is increased upon RSV wt infection, was induced less strongly by the ∆NS1 deletion mutant both in previous work and the present study." (PMID 38932114, 2024). "Specifically, in the death receptor-mediated apoptosis signaling pathway, downregulation of TNFα, TRAIL, CASP6, and CASP8 was observed, while several genes in the autophagy and mitophagy pathways showed upregulated expression post-infection." (PMID 39650642, 2024). "Infection with T. gondii increased the production of all other cytokines (IL-6, IFN-γ, TNF, IL-10, and IL-17A) in all experimental groups." (PMID 39417497, 2024). "Then, we monitored the amount of pro-inflammatory cytokines interleukin-1β (IL-1β), IL-18 and tumor necrosis factor-α (TNF-α) during infection." (PMID 39376663, 2024). "Overall, our results suggest that Gal‐1 reduces TNF‐α, IL‐6, IL‐1β, MCP‐1, RANTES‐ MIP‐1,α, and IL‐8 secretion in the human fetal membranes stimulated with LPS, mimicking an intraamniotic infection." (PMID 39575516, 2024). "The infection-specific host response at later time points was characterized by MAPK, TNF, and NFκB signaling consistent with earlier findings." (PMID 38427950, 2024). "Monocytes and macrophages are the main mediators of the inflammatory response during HCV infection, where the overproduction of TNF-α, IL-1, IL-10 and TGF-β influences the course of infection." (PMID 39608222, 2024). "Following an intraperitoneal CVB3/28 infection in DBA/2J mice, cytokine levels (MCP-1, IL-10, TNF-α, IFN-β) were quantified in homogenized cardiac tissues at different time points post-infection." (PMID 38696536, 2024). "In the context of dormant infection, we observed increased KEGG pathways representing IL17 and TNFα signaling." (PMID 39563367, 2024). "Cytokines with post-hoc statistical power > 0.7 are sCD30, SDF-1α, IFN-γ, SCYB16, M-CSF, I-309, TNF-α, IL-8, IL-18, and sTNF-R2 in SARS-CoV-2 infection vs. non-infection." (PMID 38476443, 2024). "When neonatal mouse cardiomyocytes were infected with T. cruzi isolates and stimulated with TNF-α + IFN-γ, there was an important decrease in the expression and activity of NOS2, and the effect of the infection with both isolates was similar." (PMID 39452749, 2024). "The probiotics induced the expression of immune-related genes such as IL-8, IL-1β, TNF-α, TLR-2, C3, IFN-γ, and MHC I. Additionally, these treatments increased the survival rates of grey mullet following infection with N. seriolae." (PMID 39563419, 2024). "For example, infection with Middle East Respiratory Syndrome Coronavirus (MERS-CoV) increases the levels of IFN-γ, TNF-α, and IL-17, while infection with SARS-CoV-2 leads to increased levels of IL-6, IL-12, and IFN-γ." (PMID 38355623, 2024). "Our data shows an increase in TNF-α and IL-6 but a decreased expression in IL-1β and IL-8 post DLD-1 infection." (PMID 39427065, 2024). "The expression of cytokine and chemokine genes, IL-1β, IL-6, TNF-α, IFN-γ, IL-12, and CXCLi1 in the liver of chickens were detected 3 to 5 days post-infection." (PMID 38846788, 2024).
infection (continued). "The infection of A549 cells with NTHi results in the increased secretion of TNF-α, NO, and PGE2, but significantly and dose-dependently decreases the secretion of TNF-α, NO, and PGE2 when treated with Pug-4." (PMID 38406294, 2024). "In contrast, the mock group had the highest frequencies of TNFα+ and GrzB+ CD8+ T-cells at day five post-infection, which also marked the peak of protein content in the BAL of these animals as indirect measure of tissue damage." (PMID 39472590, 2024). "Infected AMs secrete cytokines (IL-1, TNF-α, IL-12, and IL-6) and chemokines (e.g., IL-8, IP-10, MIP2, and MCP-1) to attract neutrophils, macrophages, and T cells to infection sites." (PMID 39650648, 2024). "Based on the results, the mRNA levels as well as IL-1β, IL-6, IL-8, IL-10, IL-18, TNF-α and IFN-γ were significantly upregulated, and the IL-2 level was decreased in the infection group compared to the control group (p < 0.05)." (PMID 38582846, 2024). "Post-infection, RTX-treated mice showed reduced inflammatory cytokine levels, including IL-1β, IL-6, and TNF." (PMID 39414787, 2024). "DAPT/SM-164 pretreatment was given prior to induction of cell death by tumor necrosis factor alpha (TNF-α; 100 ng/mL; 12 h), followed by subsequent infection with E. chaffeensis (MOI 50)." (PMID 37594275, 2023). "After natural infection with B. contaminans, the proportion of TNF-α/IL-2 double-producing and TNF-α/IFN-γ/IL-2 triple-producing DP T cells increased significantly." (PMID 36960295, 2023). "Conversely, infection significantly reduced levels of IL-1α, IL-2, IL-9, IL-10, IL-12 (p70), IL-13, IFNγ, IL-3, CCL4 (MIP-1β), CSF 2 (GM-CSF), CCL5 (RANTES), and TNFα." (PMID 37790429, 2023). "Murine bmDCs stimulated with an increasing multiplicity of infection (MOI) of L. acidophilus NCFM responded with a dose-dependent production of IL-12, IL-10, and TNF-α." (PMID 36769058, 2023). "CD4+ and CD8+ T cells curtail the infection by the production of IFN-γ, tumor necrosis factor alpha, and IL-2 as well as by direct cytotoxicity or lysis of infected cells." (PMID 37903443, 2023). "After infection with B. pseudomallei, HCM3 cell culture supernatants were tested with ELISA for IL-8 and TNF-α proteins." (PMID 38001928, 2023). "Plasma cytokines (IL-1β, IL-3, IL-6, IL-8, IL-18, IP-10, MIG, TNF-α, IFN-γ, MIP-1α and MIP-1β) and total peroxide (TPX) levels were quantified at baseline and at months 1 and 6 after the onset of the infection." (PMID 37894054, 2023). "The cytokines IL-6, TNF-α, and MCP-1 showed significantly higher levels in the groups treated with LT-P EVs before the infection with LT-P compared to the untreated and uninfected groups." (PMID 38138117, 2023). "The levels of TNF-α, IL-1β, and IFN-γ were first elevated after infection and then returned to baseline at 14 dpi after the peak." (PMID 37920268, 2023). "Infection with KSHV induces high levels of pro-inflammatory cytokines, chemokines and angiogenic factors such as TNF, IL-1α, IL-1β, IL-6, CXCL8, IFN-γ, VEGF, COX-2 and GM-CSF." (PMID 36634147, 2023). "Th1‐like immune response usually determines a resistant profile, leading to subclinical infection or mild to moderate disease, involving cytokines such as IFN‐γ, IL‐2, and TNF‐ α." (PMID 38053473, 2023). "TNF-α, IL-6, IL-8, IL-10, IL-13, and IL-33 in children with HRSV were significantly increased in severe infection compared to mild infection (p < 0.05) in children with HRSV." (PMID 37239461, 2023). "Several TLRs, TLR3 and TLR9 can recognize viral nucleic acids or viral protein produced by PRRSV leading to release many cytokines, such as IL-6, TNF-α and IFN-γ at the early stage of infection." (PMID 37099541, 2023). "Specific ISP groups were comparable in median time from infection to sample collection, with 155 days [IQR 146–185] for anti-CD20, 186 days [IQR 128–235] for anti-TNF, and 153 days [IQR 77.5–221] for other ISPs (p = 0.45)." (PMID 37198536, 2023).